DYRK2 (dual specificity tyrosine phosphorylation regulated kinase 2)
Diseases named in the same sentence as DYRK2 in open-access papers (continued):
Sharing a sentence is not in itself a finding about the gene and the disease.
tumor (continued). "Taken together, DYRK2, as a tumor suppressor, may inhibit metastasis via Snail phosphorylation and contribute to improved overall survival." (PMID 37886981, 2023). "Indeed, loss of both HSF1 and DYRK2 led to reduced 3D matrigel invasion and tumour burden in both ectopic and orthotopic QNBC tumour xenograft." (PMID 36622366, 2023). "Taken together, DYRK2, as a tumor suppressor, may inhibit tumor invasion and contribute to better five-year disease-free and overall survival rates." (PMID 37886981, 2023). "Notably, DYRK2 has been reported to function as a tumor suppressor; however, it has also been reported to act as an oncogene in some cancers." (PMID 37886981, 2023). "The progression of human cancer is accompanied by mutations in genes and for this reason we will investigate the relationship between mutations in the DYRK2 gene and tumors.We obtained a map of genetic alterations in DYRK2 in different tumour samples from the TCGA cohort." (PMID 36104345, 2022). "However, we still little know about the involvement of DYRK2 in certain tumour types, or the role it plays in leading to tumourigenesis." (PMID 36104345, 2022). "However, the expression level of DYRK2 in the tumor tissues of COAD, READ, KICH is less than the corresponding normal tissues with lower expression." (PMID 36104345, 2022). "Thus, the molecular features of DYRK2, such as its level of expression, tumor prognosis, phosphorylation and methylation levels, immunology and related signaling pathways, were investigated." (PMID 36104345, 2022). "In addition, phosphorylation and methylation levels of DYRK2 are different between tumor tissues and adjacent normal tissues in various tumors." (PMID 36104345, 2022). "The results state clearly that DYRK2 is a potential biomarker to predict the prognosis of tumor patients.For example,DYRK2 has been less studied in ESCA, and high DYRK2 expression may predict poor prognosis through database analysis." (PMID 36104345, 2022). "Thus, LDN192960 inhibited DYRK2 in vivo and reduced 26S proteasome activity and thereby targeted proteasome-dependent neoplastic diseases such as TNBC and MM." (PMID 33376136, 2021). "In addition, curcumin impedes 26S proteasome activity via DYRK2 inhibition, and its treatment significantly reduced tumor volume in a TNBC mouse xenograft model." (PMID 33611659, 2021). "Furthermore, phosphorylation of the transcription factors MYC and JUN by DYRK2 is required for their degradation in the G1/S transition of the cell cycle, an event which is also tumor progression relevant." (PMID 33937075, 2021). "Indeed, in an ectopic nude mouse xenograft model, DYRK2 KO and T25A Rpt3 knock-in cells were less efficient in generating a tumor as compared to parental cells." (PMID 33376136, 2021). "Crispr/Cas9-mediated DYRK2 deletion in MDA-MB-231 or MDA-MB-468 cells showed that tumors derived from TNBC–DYRK2–deficient cells had significantly slower growth rates and lower tumor burden than those derived from their parental cells." (PMID 33376136, 2021). "The knockdown of DYRK2 increases cell proliferation in cancer cells and tumor progression." (PMID 34671097, 2021). "Seemingly, in this case, DYRK2 inhibition led to tumor suppression." (PMID 33376136, 2021). "We have previously shown that DYRK2 exerts anti-tumor effects in various cancer cells." (PMID 34671097, 2021). "Although it has been suggested that DYRK2 might have both a “tumour suppressor” and a “tumour promoter” role, our data support the hypothesis that in TNBC DYRK2 acts as a “tumour promoter”." (PMID 33268814, 2021). "Besides the cell cycle, DYRK2 also regulates cell factors involved in other processes crucial for tumor progression, such as apoptosis or DDR." (PMID 32751160, 2020).
tumor (continued). "The data showing the correlation in the levels of both proteins in tumour tissue agree with our in vitro data and suggest that the degradation of Notch1-IC by DYRK2 might also be relevant in cancer patients." (PMID 31605148, 2020). "Furthermore, the lower DYRK2 levels were correlated with tumor sites (P = 0.023), advanced clinical stages (P = 0.006) and shorter survival in the advanced clinical stages." (PMID 27532268, 2016). "The reported roles of Dyrk2 in the tumor biology appear rather controversial." (PMID 24676346, 2014). "However, in the light of all these potential tumor suppressor activities it is fair to ask why Dyrk2 is strongly overexpressed in several tumor entities." (PMID 24676346, 2014). "However, more recent studies point to a reduced or abolished Dyrk2 expression in multiple human tumor types, which correlates with invasiveness in the case of human breast cancer." (PMID 24676346, 2014). "In addition, tumor growth was inhibited by DYRK2 downregulation in xenograft mouse models." (PMID 37886981, 2023). "Furthermore, knock-down of DYRK2 significantly inhibited tumor growth of PCa in a xenograft model." (PMID 35614066, 2022). "In addition, knock-down of DYRK2 significantly inhibited tumor growth in vivo." (PMID 35614066, 2022). "Importantly, in tumours from TNBC patients, DYRK2 levels positively correlate with active HSF1 and associates with poor prognosis, suggesting that DYRK2 could be promoting TNBC." (PMID 33268814, 2021). "Furthermore, our data suggest that nuclear DYRK2 might be the pool responsible for its HSF1-dependent tumour promoter role in TNBC." (PMID 33268814, 2021). "Although the molecular function of DYRK2 suggests its tumor suppressive role, it may act as a tumor promoter in “proteasome-addicted” tumors by increasing proteasome-mediated protein degradation through phosphorylation of Rpt3, the 19S subunit of the proteasome." (PMID 33842469, 2021). "DYRK2 phosphorylates, stabilizes and activates HSF1, thus promoting tumor growth by maintaining proteostasis in cancer cells." (PMID 41028522, 2025). "However, another study reported that DYRK2 expression and clinicopathological features were strongly associated with tumor site, stage, nodal classification, metastasis, and mortality, but not with sex, age, or tumor differentiation." (PMID 37886981, 2023). "In tumor tissues, KLF4 showed elevated expression levels in cell lines enriched with CSCs and maintained self-renewal of CSCs by targeting dual-specificity tyrosine-(Y)-phosphorylation-regulated kinase 2 (DYRK2) and inducing telomerase expression." (PMID 36761967, 2023). "Taken together, these findings demonstrate that DYRK2 participates in the degradation of multiple FBXW7 substrates and reveals DYRK2 as a general modulator of FBXW7 activity with potential consequences in the damage response and tumor progression." (PMID 36934104, 2023). "To answer this question, we evaluated the tumour formation capacity of MDA-MB-231 parental and HSF1-KO TNBC cells after DYRK2 knock-down by shRNA." (PMID 36622366, 2023). "In contrast, DYRK2 overexpression in Huh1 and PLC/PRF5 cell lines using an adenoviral vector suppressed cyclin D1 and D2 and c-Myc expression, tumor growth, and colony formation." (PMID 37886981, 2023). "Altogether, this work reveals a new regulatory axis, DYRK2/FBXW7, which provides an understanding of the role of these two proteins in tumor progression and DNA damage responses." (PMID 36934104, 2023).
tumor (continued). "This clearly suggests that dual inhibition of DYRK2 and HSF1 will impede tumour growth in vivo at an enhanced rate compared with individual targeting." (PMID 36622366, 2023). "Recent research demonstrated that miR-183-5p can increase HCC cell proliferation by suppressing the expression of tumor suppressors (including AKAP12, DYRK2, FOXN3, FOXO1 and LATS2) which is agreement with our results." (PMID 37168369, 2023). "We had observed this correlation previously at protein levels wherein nuclear DYRK2 expression positively correlated with nuclear HSF1 and this dual expression predicted poor patient prognosis in TNBC tumour samples." (PMID 36622366, 2023). "DYRK2 is the only kinase that was found to be significantly downregulated in CRC, and was reported to have a tumor suppressor role in CRC." (PMID 35454940, 2022). "Some molecules express the proliferation of tumor cells while producing CAM-DR, which is consistent with the clinical practice that is not sensitive to the treatment of indolent lymphomas, such as DYRK2." (PMID 34295898, 2021). "In contrast with these findings, other studies have used MDA-MB-231–derived xenografts and reported DYRK2 control EMT by degrading SNAIL and promoting transcription factor Krüppel-like factor 4 expression, thereby functioning as a tumor suppressor." (PMID 33376136, 2021). "Of interest, the four protein kinases that show negative regulation of SIAH2 (activity and/or stability), namely HIPK2, DYRK2, CHK2, and PLK3, are all considered to have tumor suppressive functions and with roles in the DNA damage response." (PMID 33842469, 2021). "This link between DYRK2 and HSF1 is also observed in TNBC tumor samples, wherein a marked correlation was observed between high DYRK2 levels and high nuclear HSF1 levels." (PMID 33376136, 2021). "The Kruppel-like factor 4 transcription factor has been shown to repress DYRK2 expression, acting directly on the DYRK2 promoter in chronic myeloid leukemia (CML) cell lines and mouse models, thereby favoring tumor progression." (PMID 32751160, 2020). "Functional studies confirmed that DYRK2 inhibited cell invasion and migration in both HCT116 and SW480 cells and functioned as a tumor suppressor in CRC cells." (PMID 27532268, 2016). "Taken together, these data confirmed that DYRK2 inhibited cell proliferation, invasion and migration in both HCT116 and SW480 cells and functioned as a tumor suppressor in CRC cells." (PMID 27532268, 2016). "Taken together, these data confirmed that DYRK2 inhibited cell invasion and migration in both HCT116 and SW480 cells and functioned as a tumor suppressor in CRC cells." (PMID 27532268, 2016). "We initially investigated recently reported single-cell RNA sequencing (sc-RNAseq) datasets across a few different cancers and queried whether DYRK2 and HSF1 expression overlapped between the heterogenous cell populations within diverse tumours." (PMID 36622366, 2023). "DYRK2 is an important regulator of CRC cell proliferative, invasive, and migratory activity, functioning by regulating Twist and thereby modulating EMT induction, chemosensitivity, and apoptosis in these tumor cells." (PMID 36577753, 2022). "As such, in the present study we sought to conduct an in-depth analysis of the role of DYRK2 as a mediator of CRC cell chemoresistance, with a specific focus on its ability to regulate EMT induction through analyses of human tumor tissue samples, CRC cells, and animal model systems." (PMID 36577753, 2022). "Both DYRK1A and DYRK2 showed a significantly lower expression in READ tumor vs. normal tissues, whereas DYRK1B, DYRK3 and DYRK4 had no significant change in expression." (PMID 35454940, 2022).
tumor (continued). "Next, as a first approximation to address if DYRK2 regulates HSF1 in vivo, we asked whether the levels of DYRK2 correlate with HSF1 levels in tumour tissue from TNBC patients." (PMID 33268814, 2021). "Finally, in order to investigate the clinical significance of our findings, we first analysed data from the public database The Human Protein Atlas to determine the protein abundance of DYRK2 and NOTCH1 in tumour tissues." (PMID 31605148, 2020). "Notably, DYRK2 expression was related to the clinicopathological features of age and tumor sites but not to sex, clinical stage, tumor-node-metastasis (TNM) classification, or pathological differentiation." (PMID 37886981, 2023). "In contrast, DYRK2 expression did not correlate with gender, age and tumor differentiations." (PMID 27532268, 2016). "Although the expression of some molecules can reduce the proliferation of tumor cells, the production of CAM-DR is consistent with the clinical practice that is not sensitive to the treatment of inert lymphomas, such as DYRK2." (PMID 34295898, 2021).
cancer (40 papers, 2015 to 2026). A tumor composed of atypical neoplastic, often pleomorphic cells that invade other tissues. "DYRK2 is a key regulator of DNA damage response pathways and stress signals, and it has been implicated in several human cancers with both oncogenic and antitumor suppressor activities." (PMID 34363019, 2022). "It is not difficult to find a statistically positive correlation between DYRK2 expression and the estimated infiltration value of cancer-associated fibroblasts for cases of BLCA, BRCA-LumA, HNSC [HPV (Human papillomavirus) + / −], LUSC, OV, PAAD,SARC and SKCM." (PMID 36104345, 2022). "In fact, phosphoproteomics studies show that these cancer mutations significantly alter substrate specificity of DYRK2 in cells." (PMID 33376136, 2021). "In DYRK2, specific loss-of-function mutations have been reported in cancer, which affect either the activity of the kinase or impede its ability to form functional complexes with interactors." (PMID 33376136, 2021). "The data show that altered protein-protein interactions caused by the mutations are associated with topological changes and affected phosphorylation of known cancer driver proteins, thus linking Dyrk2 mutations with cancer-related biochemical processes." (PMID 32678104, 2020). "The results highlight the complexities of the cellular response to perturbations and provide insights how specific mutations in the Dyrk2 kinase shape cancer-relevant biochemical pathways." (PMID 32678104, 2020). "The fact that certain point mutations in Dyrk2 substantially disrupt the binding to CDPs supports the putative importance of these mutations in cancer-related processes." (PMID 32678104, 2020). "Here, the authors present an integrated proteomic workflow to determine the molecular response of cells to different cancer-associated mutations of the kinase Dyrk2." (PMID 32678104, 2020). "We identified Dyrk2 SX and Dyrk2 RL as cancer-associated mutants with the strongest impact on the phosphorylation and interaction to CDPs, suggesting a contribution of these mutants, probably together with other factors, in cancer progression." (PMID 32678104, 2020). "We have also gathered available information from different bioinformatic resources to show DYRK2 interactome, normal and tumoral tissue expression, and recurrent cancer mutations." (PMID 32462403, 2020). "DYRK2 was reported to be not only associated with cancer cell growth but also with cancer metastasis." (PMID 27532268, 2016). "DYRK2 is associated with the anti-cancer effect of 5-fluorouracil (5-FU)." (PMID 37886981, 2023). "Specifically, DYRK2 has been mainly implicated in cancer progression." (PMID 36161154, 2022). "Importantly, accumulating studies have demonstrated that DYRK2 is downregulated in various cancer tissues, and that low DYRK2 expression is closely associated with a poor prognosis." (PMID 34671097, 2021). "However, various studies have shown that DYRK2 is down-regulated in various cancer tissues such as lung, breast, prostate and colon, associated with poor patient prognosis." (PMID 31605148, 2020). "Furthermore, we found a clear effect of some cancer-related Dyrk2 mutations on the interaction with CDPs." (PMID 32678104, 2020). "DYRK2’s role in apoptosis, the programmed cell death mechanism vital for cancer cell elimination, is also noteworthy." (PMID 38474160, 2024). "Owing to these functions, DYRK2 is thought to regulate tumorigenesis, and its function in cancer has been investigated." (PMID 37886981, 2023). "This way, the DYRK2, a major adenosine triphosphate (ATP)-dependent phosphorylase in eukaryotic cells, has also been proven as a feasible upstream molecular target in cancer therapy." (PMID 37108565, 2023).